AATBC (apoptosis associated transcript in bladder cancer)
Gene: Long non-coding RNA gene on chromosome 21 (43,805,758 to 43,812,567, reverse strand). Ensembl gene ENSG00000215458.
Diseases named in the same sentence as AATBC in open-access papers:
AATBC is named in the same sentence as 10 diseases in open-access papers, as found by Europe PMC text mining. Sharing a sentence is not in itself a finding about the gene and the disease. The quoted sentences say what the papers report.
bladder cancer (7 papers, 2015 to 2025). "The lncRNA AATBC (Apoptosis Associated Transcript in Bladder Cancer) has been studied for its role in cancer but is also involved in mitochondrial function." (PMID 39846682, 2025). "AATBC (Apoptosis-Associated Transcript in Bladder Cancer) is a multifunctional lncRNA involved in metabolism and cancer." (PMID 40724881, 2025). "In this study, we identified AATBC (apoptosis‐associated transcript in bladder cancer, LOC284837) as a novel lncRNA." (PMID 32364663, 2020). "In this report, we identified another novel lincRNA, termed as AATBC (Apoptosis-Associated Transcript in Bladder Cancer, also known as LOC284837)." (PMID 25473900, 2015). "We found that AATBC was overexpressed in bladder cancer tissues compared with adjacent non tumor tissues and positively correlated with tumor grade and pT stage, implying that AATBC might be an useful diagnostic biomarker or therapeutic target in bladder cancer." (PMID 25473900, 2015). "lncRNA AATBC is overexpressed in bladder cancer tissues and positively correlated with tumor grade and stage." (PMID 34122546, 2021). "This phenomenon was further demonstrated by the relative changes of biological behaviors in bladder cancer cell lines after AATBC knockdown." (PMID 25473900, 2015). "Our results showed that the knockdown of AATBC by RNAi technology led to the apoptosis of bladder cancer cells via the intrinsic apoptosis signal, as shown by the activation of caspase-9 and caspase-3." (PMID 25473900, 2015). "We found that AATBC was overexpressed in bladder cancer patient tissues and positively correlated with tumor grade and pT stage." (PMID 25473900, 2015). "We further verified the expression pattern of AATBC in bladder cancer cell lines (T24, EJ, UM-UC-3 and 5637) and an immortalized normal urothelium cell line SV-HUC-1 by quantitative RT-PCR, using β-actin as a reference gene." (PMID 25473900, 2015). "AATBC expression was positively correlated with tumor grade and pT stage of bladder cancer." (PMID 25473900, 2015). "We found that AATBC was overexpressed in bladder cancer tissues and cancer cell lines." (PMID 25473900, 2015). "Taken together, our study indicated that AATBC might play a critical role in pro-proliferation and anti-apoptosis in bladder cancer by regulating cell cycle, intrinsic apoptosis signaling, JNK signaling and NRF2." (PMID 25473900, 2015). "Moreover, it has been demonstrated that knockdown of AATBC could prevent cell proliferation in bladder cancer." (PMID 27863388, 2016). "AATBC could be a potential therapeutic target for bladder cancer." (PMID 25473900, 2015). "AATBC may be an important regulator of apoptosis in bladder cancer." (PMID 25473900, 2015). "Therefore, the pro-apoptotic effect of AATBC knockdown in bladder cancer may achieved through activation of JNK signaling and suppression of NRF2." (PMID 25473900, 2015). "Moreover, cisplatin induction could significantly strengthen the pro-apoptotic ability of AATBC knockdown, indicating that apoptosis via AATBC inhibition could enhance the chemosensitivity of bladder cancer cells and AATBC might be an attractive therapeutic target in bladder cancer treatment." (PMID 25473900, 2015).
breast carcinoma (4 papers, 2021 to 2024). "lncRNA AATBC could promote breast cancer migration and invasion through binding with YBX1 to activate the YAP1/Hippo signaling pathway." (PMID 34244473, 2021). "In breast cancer, lncRNA AATBC functions as a Y-box binding protein 1 (YBX1) scaffold and controls Hippo signaling through lncRNA AATBC/YBX1/mammalian sterile 20 like kinase 1 (MST1) axis." (PMID 39313797, 2024). "LncRNA AATBC activates the YAP1/Hippo signaling pathway through the AATBC-YB-1-MST1 axis, promoting breast cancer migration and invasion." (PMID 35406781, 2022).
nasopharyngeal carcinoma (4 papers, 2020 to 2024). A carcinoma arising from the nasopharyngeal epithelium. "AATBC was found to be highly expressed in nasopharyngeal carcinoma (NPC), and increased AATBC expression was associated with poor survival in patients with NPC." (PMID 32364663, 2020). "lncRNA AATBC was reported to promote the occurrence and development of nasopharyngeal carcinoma by regulating pinin through the mir-1237-3P-PNN-ZEB1 axis." (PMID 34122546, 2021). "In nasopharyngeal carcinoma (NPC), lncRNA AATBC was significantly expressed and upregulated desmosome-associated protein pinin (PNN) expression by miR-1237-3p sponging." (PMID 39313797, 2024).
melanoma (3 papers, 2021 to 2025). A malignant, usually aggressive tumor composed of atypical, neoplastic melanocytes. "In a series of in vitro experiments in A375 cell lines, we demonstrated that the overexpression of AATBC in melanoma plays an important role in poor prognosis." (PMID 34122546, 2021). "Cell experiments have verified that knocking down AATBC in A375 cell lines can reduce the proliferation and invasion ability of melanoma cells." (PMID 34122546, 2021). "In this study, AATBC was knocked out, and a significant reduction in melanoma cell activity was observed." (PMID 34122546, 2021). "Moreover, AATBC was included in a melanoma prognostic model related to gene instability, where its knockdown reduced melanoma cell proliferation and invasion." (PMID 40724881, 2025). "created a novel signature based on five lncRNAs, including AATBC, AC145423.2, LINC01871, AC125807.2 and AC245041.1, that can predict the clinical outcome in melanoma patients." (PMID 38193829, 2024).
prostate carcinoma (3 papers, 2022 to 2025). A carcinoma that arises from epithelial cells of the prostate gland. "The lncRNA AATBC binds miR‐1245b‐5p as an oncogene and promotes malignant progression of prostate cancer through the miR‐1245b‐5p/LIN2 axis, and the downstream molecule LIN2 plays a pro‐oncogenic role in prostate cancer progression." (PMID 40801824, 2025).
E. coli infection (1 paper, 2017). "As one example, we found the lncRNA AATBC to show different isoforms during E. coli infection and treatment with vitamin D or atRA." (PMID 28094339, 2017).
lung carcinoma (1 paper, 2024). "The expression of lncRNA GIAT4RA and lncRNA AATBC was significantly related to the stage of lung cancer." (PMID 39313797, 2024). "Since miR-1237-3p is expressed in lung cancer, therefore, lncRNA AATBC may function as ceRNA of PNN gene by competitively interacting with miR-1237-3p and eventually increasing lung cancer via miR-1237-3p/PNN/ZEB axis." (PMID 39313797, 2024). "Furthermore, poor survival in patients with lung cancer was indicated by high expression of lncRNA AATBC, SMARCB1, and concentration of NSE." (PMID 39313797, 2024). "Consequently, lncRNA AATBC may promote lung cancer migration by activating the Hippo pathway through the lncRNA AATBC/YBX1/MST1 axis." (PMID 39313797, 2024). "On the other hand, patients with lung cancer had statistically positive correlations between each of lncRNA GIAT4RA, lncRNA AATBC, lncRNA Sirt1-AS, and SMARCB1 except between lncRNA AATBC, and lncRNA Sirt1-AS (P = 0.074)." (PMID 39313797, 2024). "As a result, this study assesses the expression profiles of lncRNA GIAT4RA, lncRNA AATBC, lncRNA Sirt1-AS, and SMARCB1 genes in lung cancer patients." (PMID 39313797, 2024). "So, this study aimed to evaluate the expression profiles of lncRNA GIAT4RA, lncRNA AATBC, lncRNA Sirt1-AS, and SMARCB1 in lung cancer." (PMID 39313797, 2024).
Obesity (1 paper, 2025). Accumulation of substantial excess body fat. "AATBC is currently considered a novel regulator of adipocyte plasticity and mitochondrial function in humans, with a potential link to obesity." (PMID 41169019, 2025).
tumor (6 papers, 2015 to 2022). "AATBC knockdown resulted in inhibition of proliferation and increased apoptosis in vitro and suppressed tumor growth in vivo." (PMID 25473900, 2015). "Down regulation of AATBC resulted in effectively suppressed proliferation in vitro, concomitant with induction of cell cycle arrest and apoptosis, and inhibited tumor growth in NOD/SCID mice in vivo." (PMID 25473900, 2015). "To investigate the biological significance of AATBC knockdown on tumor growth in vivo, we proceeded with the research through the establishment of a subcutaneous xenograft tumor model in NOD/SCID mice." (PMID 25473900, 2015). "Additionally, transwell Matrigel invasion assays showed that AATBC knockdown effectively inhibited tumor cell invasion, while overexpression of AATBC enhanced the invasion." (PMID 32364663, 2020). "Studies have revealed that AATBC, ADAMTSL4-AS1, EPB41L4A-AS1, MIA-RAB4B, MIR4697HG, GAS5, SNHG12, MSX2P1, and LINC00852 are related to tumorigenesis and tumor progression in multiple cancers, such as bladder, breast, colorectal, and ovarian." (PMID 31850068, 2019). "As expected, suppression of AATBC expression in UM-UC-3 cells treated with shRNA resulted in lower mean tumor mass compared to that of negative control group (0.36 g vs 1.085 g, P<0.05)." (PMID 25473900, 2015).
cancer (4 papers, 2015 to 2025). A tumor composed of atypical neoplastic, often pleomorphic cells that invade other tissues. "In our study, the flow cytometry analysis and EdU incorporation assay demonstrated that AATBC down-regulation induced cell cycle arrest at the G1 phase and lower percentage of cancer cells in S phase." (PMID 25473900, 2015). "Notably, the lnc2cancer database does not report AATBC overexpression in HNSCC, and no published studies to date have explored its role in this cancer type." (PMID 40724881, 2025).